PKP2 (plakophilin 2)
Diseases named in the same sentence as PKP2 in open-access papers (continued):
Sharing a sentence is not in itself a finding about the gene and the disease.
cardiomyopathy (continued). "In humans, heterozygous PKP2 and DSG2 mutations lead to ARVC, but in mice, homozygous deletion of Dsg2 and Pkp2 in the mouse heart is required to elicit cardiomyopathy and to define NF-κB activation, since heterozygous deletion has little phenotype in mice." (PMID 38768074, 2024). "The Invitae Arrhythmia and Comprehensive Cardiomyopathy panel identified two pathogenic variants in the desmoplakin (DSP, c.5028_5031del) and plakophilin-2 (PKP2, c.1912C>T) genes, confirming the underlying genetic cause for her presentation." (PMID 39185139, 2024). "There was an excess burden of splice-disrupting variants in PKP2 (5.9%), FLNC (2.7%), TTN (2.8%), MYBPC3 (8.2%) and MYH7 (1.3%), in distinct cardiomyopathy subtypes, and KCNQ1 (3.6%) in long QT syndrome." (PMID 37821546, 2023). "The PKP2 cardiomyopathy is inherited autosomally dominantly and is thought to affect primarily the RV, making it specifically associated with ARVC." (PMID 36556128, 2022). "In combination with this, the knowledge that truncating variants are very likely disease causing and particularly for ARVC will aid in the diagnosis and care of patients with PKP2 cardiomyopathy and their families." (PMID 34120153, 2021). "We show that truncating variation at any position along the PKP2 transcript explains a large EF of PKP2 cardiomyopathy, and highlight missense variation at the C-terminus of the PKP2 transcript encoding a potential unrecognized functional domain." (PMID 34120153, 2021). "Here, we employ clinical genetic testing cohorts, highly phenotyped definite ARVC cohorts, and population genomic data with and without associated clinical information to describe the genetic architecture of PKP2 cardiomyopathy." (PMID 34120153, 2021). "Aberrant regulation of these genes, including PKP2, ITGA6, and seven are important for cytoskeleton and cell-cell and cell-matrix interactions and are associated with cardiomyopathy, arrhythmogenic R ventricular cardiomyopathy and hypertrophic cardiomyopathy." (PMID 32477331, 2020). "Three cases (34, 286 and 290) had one variant in a cardiomyopathy gene and one in a channelopathy gene (CSRP3 and TRPM4, PKP2 and ANK2, MYH7 and KCNH2, respectively)." (PMID 30615648, 2019). "A cardiac-specific, tamoxifen-activated PKP2 knock-out murine model (PKP2cKO) was used to define the effect of adenosine receptor blockade on the progression of a PKP2-dependent cardiomyopathy." (PMID 30568602, 2018). "Considering rare variants for each cardiomyopathy type, in ARVC patients, the highest number of rare variants was found in TTN and RYR2 genes (4 variants) followed by OBSCN and PKP2 (3 variants)." (PMID 28750076, 2017). "Ventricular cardiomyocytes isolated from inducible-PKP2-KO (PKP2-cKO) mice before the appearance of overt cardiomyopathy (i.e., still-intact tissue) have a widened intercellular space and display Cx43 remodeling and HC lateralization in the right but not the left ventricle." (PMID 36919695, 2023). "Our data presented potential important disease mechanisms in a PKP2-related cardiomyopathy." (PMID 31438494, 2019). "Since the environmental and genetic modifiers of ACM remain unknown, we examined the effect of exercise, cardiac pressure overload, and inflammation on the progression of a PKP2-related cardiomyopathy." (PMID 31438494, 2019). "Considering that clinically cardiomyopathies are diseases with a progressive course, one cannot exclude that DCM cases carrying Pkp2 variants could be cases of advanced ACM which were missed in the initial disease phases." (PMID 30619891, 2018). "However, the role of this mechanism in the heart, and in the specific case of a PKP2-initiated cardiomyopathy, remains unexplored." (PMID 30568602, 2018). "PKP2: The PKP2 gene encodes the desmosomal protein plakophilin-2 (PKP2), mutations of which have been identified in a small number of patients with features of BrS, without apparent structural cardiomyopathy." (PMID 37443825, 2023).
cardiomyopathy (continued). "Given the specificity of PKP2 cardiomyopathy for the ARVC phenotype in particular, we hypothesized that of the ACM probands and PKP2 missense variants in the Clinical Genetic Testing Cohort (N = 40, solid blue box), those with ARVC-specific diagnosis would be enriched in predicted windows (N = 16)." (PMID 34120153, 2021). "However, important questions regarding the genetic architecture of PKP2 cardiomyopathy remain." (PMID 34120153, 2021). "The modifier roles of the PVs or LPVs in the PKP2, DSP, SCN10A, and others identified in the family members benefit from biological plausibility and the well-established roles of these genes in cardiomyopathies and/or arrhythmias." (PMID 34790974, 2021). "This is further exemplified in PKP2 Het mutant mice, which exhibited a latent phenotype on survival and primarily exhibited arrhythmias in the absence of cardiomyopathy when assessed over the same and longer timeframes as PKP2 Hom mice." (PMID 39196150, 2023). "This plakophilin-2 (PKP2) dependent electropathy progresses regardless of structural disease and can also present with exercise-induced symptoms before overt cardiomyopathy develops." (PMID 38034271, 2023). "A more recent investigation focused on the early events driving the remodeling of the Ca2+ handling machinery in RV-derived PKP2-cKO (Pkp2-cKO-RV) cardiomyocytes isolated 14 days after tamoxifen injection, i.e., when cardiomyopathy was not evident yet." (PMID 31426283, 2019). "In humans, PKP2 variants are transmitted in an autosomal-dominant manner and mutation carriers can proceed throughout life without developing any signs of cardiomyopathy, similar as observed in the PKP2-Hz mouse model." (PMID 31438494, 2019). "Regardless, PKP2 Het mutant mice will provide a unique model to exacerbate and tease out the arrhythmogenic substrate and mechanisms underlying ARVC in the absence of cardiomyopathy in the future, which is also reminiscent of the early concealed phase of ARVC." (PMID 39196150, 2023). "The association between Pkp2 mutations and idiopathic SCD is not that surprising, considering that often SCD is the earliest manifestation in ACM athletes before the onset of overt cardiomyopathy." (PMID 30619891, 2018).
Arrhythmia (32 papers, 2008 to 2026). Any cardiac rhythm other than the normal sinus rhythm. "Preclinical studies using adeno-associated virus vector–mediated delivery of the human PKP2 gene to PKP2-deficient mice prevented RV dilation, left ventricular functional decline, and reduced arrhythmia burden." (PMID 40883071, 2025). "Disruption of the connexome alters the activity of sodium channels including SCN5A and contributes to arrhythmias in ARVC patients with PKP2 or JUP mutations." (PMID 38370698, 2024). "In this study, we present a male patient with ARVD who underwent a genetic test that revealed ARVD with PKP-2 mutation after multiple admissions for heart failure and arrhythmias." (PMID 35698692, 2022). "This is in agreement with an enhanced susceptibility to isoproterenol induced arrhythmias in PKP2-cKO hearts." (PMID 34630150, 2021). "Here, we propose a role for RyR2 dysfunction and NCX modulation as potential targets for the prevention/treatment of arrhythmias resulting from loss of PKP2 function." (PMID 34630150, 2021). "More recently, distinct connexin-mediated mechanisms were implicated in driving cardiac arrhythmias associated with PKP2 loss." (PMID 34765046, 2021). "Previous studies have demonstrated that mutations in ANK2 and PKP2 have been associated with ion channel dysfunction leading to cardiac arrhythmias." (PMID 34281161, 2021). "Impaired intracellular Ca2+ dynamics (as shown in the three- and six-month-old mice) in combination with endurance exercise possibly increases the susceptibility towards arrhythmias in PKP2-Hz hearts." (PMID 31438494, 2019). "Transcriptomic analysis suggested that loss of Pkp2 may alter intracellular calcium homeostasis, predisposing to arrhythmias." (PMID 38892395, 2024). "Therefore, PKP2 gene mutations can alter the functioning of sodium channels, and so the onset of arrhythmias." (PMID 38473714, 2024). "Altogether, these results indicate that overexpression of mutant Pkp2 might have a dose-dependent pathogenic effect in mice and that this protein has a possible role in predisposition to arrhythmia." (PMID 38892395, 2024). "This is in agreement with recent experimental data from a novel murine model with cardiac‐specific, tamoxifen‐triggered PKP2 deficiency: PKP2 deficiency increased RyR2‐mediated Ca2+ release from the sarcoplasmic reticulum, leading to catecholamine‐induced arrhythmias." (PMID 33784018, 2021). "Although SCN5A mutations (gene coding for Nav1.5) are directly linked to the inherited cardiac arrhythmia, Brugada syndrome, a retrospective analysis of Brugada patients identified that a subgroup of these patients harbored missense mutations in PKP2." (PMID 34765046, 2021). "Mutations and expression of key NaV1.5 interacting proteins like α1-syntrophin, calveolin-3, plakophilin-2, and others are known to influence the expression and function of the NaV1.5 channel and are linked to increased risk for cardiac arrhythmias and sudden cardiac death." (PMID 30081552, 2018). "Interestingly, all patients with arrhythmia were male and proband, and one of them was a carrier of anARVD/C-associated pathogenic mutation (plakophilin-2)." (PMID 27580740, 2016). "However, none of these studies focused on the underlying mechanisms by which calcium-handling abnormalities due to PKP2 loss-of-function may lead to arrhythmias." (PMID 34630150, 2021). "Defective RYR2 gating and the associated aberrant Ca2+ release from the SR during diastole trigger arrhythmia initiation in PKP2 cKO mice." (PMID 41468454, 2025). "Second, our study designs and data interpretation were focused on how cardiac function, arrhythmia, and animal survival responded to the gene therapy and on determination of the PKP2 dose-function relationship." (PMID 38499690, 2024). "Eight of these associations were novel (LMNA, SMAD6, HSPB9, TMEM95, KLF1, TET2, NME3, KDM5B) and 5 genes have previously been linked to arrhythmias (SCN5A, TTN, RPL3L, PKP2, PMVK)." (PMID 38390584, 2024).
Arrhythmia (continued). "Pkp2-cKO mice were given a single systemic dose via retro-orbital injection of TN-401 at 3E13 or 6E13 vg/kg one week before tamoxifen induction of cardiac Pkp2 gene deletion and cardiac function and arrhythmias were evaluated at 4 and 9 weeks post induction." (PMID 38499690, 2024). "The number of sedentary PKP2+/- mice showing induced arrhythmias upon ISO was unaltered compared to WT (40% inducibility, p = 0.653)." (PMID 34086773, 2021). "Previous studies have used computer models to demonstrate the role of aberrant sodium-current kinetics in facilitating reentry-based arrhythmias upon reduced presence of PKP2, or to confirm the experimentally observed calcium-handling abnormalities." (PMID 34630150, 2021). "Surprisingly, after 16 weeks of running, only 17% of PKP2+/- mice (n = 6) had inducible arrhythmias, which was increased to 67% by ISO (p = 0.079 vs. basal)." (PMID 34086773, 2021). "In contrast, we found an increased propensity towards arrhythmia in PKP2+/- mice already at baseline, which is in line with our finding of increased β-AR protein expression in PKP2+/-." (PMID 34086773, 2021). "To evaluate potential mechanisms leading to a higher propensity for arrhythmias in PKP2+/- mice at rest, we measured the protein levels of β1-adrenergic receptor (β1-AR)." (PMID 34086773, 2021). "Reduced Cx43 expression and localization to the intercalated disc were observed in heterozygous human PKP-2 volunteers, which potentially explains the delayed conduction and propensity to develop arrhythmia in this disease." (PMID 25667661, 2015). "Altogether, these studies highlight the crucial role of PKP2 in the pathogenesis of ACM and in maintaining gap junction integrity, leading to the hypothesis that loss of PKP2 predisposes to arrhythmias in patients." (PMID 38892395, 2024). "TN-401 treatment of Pkp2-cKO mice showed dose-dependent efficacy in preventing decline of LV ejection fraction, reducing RV dilation as estimated by RV area normalized to body weight, and a trending reduction in arrhythmias." (PMID 38499690, 2024). "Pressure overload increased levels of fibrosis in PKP2-Hz hearts, without affecting the susceptibility towards arrhythmias." (PMID 31438494, 2019). "Presence of PKP-2 mutations in ARVC correlates with earlier onset of symptoms and arrhythmias." (PMID 25315082, 2014). "Telemetry ECG recordings revealed that conscious PKP2 Hom mice had isolated PVCs that precipitated into ventricular tachycardia and fibrillation, further suggesting that ventricular depolarization abnormalities can serve as a primer for life-threatening arrhythmias." (PMID 39196150, 2023). "Finally, pro-adipogenic factors have been used previously to demonstrate calcium dysregulation and lipogenesis in myocytes derived from iPSCs with a PKP2 mutation, but important arrhythmia substrates such as reduced CV and APD were not reported." (PMID 36294819, 2022). "Yet, they imply possible new avenues of investigation in humans, namely to examine the role of intracellular calcium homeostasis as an arrhythmia trigger and as a therapeutic target in patients with mutations in PKP2, even in the absence of overt structural disease." (PMID 28740174, 2017). "In that context, we hypothesize that mutations in PKP2 could underlie some catecholamine-sensitive life-threatening arrhythmias in young individuals even in the absence of structural disease, thus leading to a clinical diagnosis of CPVT." (PMID 28740174, 2017). "KCNQ1/KCNH2 suppression-and-replacement, SCN5A base editing, and structural protein restoration via PKP2 and TMEM43 have each demonstrated capacity to re-establish electrophysiological stability in arrhythmia models." (PMID 42193469, 2026). "Additionally, in vivo validation in PKP2+/− rats corroborated these findings: KA (20 mg/kg/day, i.g.)can improve the wide QRS waveform and alleviate arrhythmia." (PMID 40771922, 2025).
Arrhythmia (continued). "Because PKP2 knockout is embryonic lethal, a cardiac-specific inducible PKP2 knockout mouse was generated, which had many of the characteristic ARVC phenotypes: fibrosis, remodeling, reduced ejection fraction, arrhythmia, and sudden death." (PMID 37775650, 2023). "Furthermore, in contrast with result obtained in untreated animals, flecainide-treated PKP2-cKO mice showed absence of ISO-induced arrhythmia burden in the total recording period (20 min)." (PMID 28740174, 2017).
Ventricular arrhythmia (21 papers, 2018 to 2025). "In particular, the alteration of αT-catenin, as well as PKP2 and Connexin 43, is associated with electrical conduction abnormalities, ventricular arrhythmias and sudden cardiac death." (PMID 38473714, 2024). "PKP2 variant carriers showed a stronger association with ventricular arrhythmias (OR 11.90 [95% CI 4.38; 27.86], p = 6.4×10–6) compared with heart failure (OR 1.50 [95% CI 0.48; 3.64], P=0.395)." (PMID 36264615, 2022). "Although many previous studies indicated that the presence of desmosomal gene mutations as well as PKP2 mutations is associated with a higher incidence of ventricular arrhythmias, this observation was not confirmed by our results." (PMID 34191271, 2021). "Acute adrenergic stimulation of PKP2 null mice associates with malignant ventricular arrhythmias and sudden death, mimicking exercise during the concealed phase of the disease." (PMID 31438494, 2019). "Finally, a Cox proportional hazards model suggested significant differences in ventricular arrhythmia–free survival between 4 PKP2 founder variants, including c.1211dup." (PMID 37505369, 2023). "Therefore, the decreased SERCA2a levels observed in this study may be related to PKP2 downregulation and an increased risk of ventricular arrhythmia." (PMID 41468454, 2025). "A Phase 1/2, open-label, dose-escalating, multicenter trial (NCT06109181) is evaluating the efficacy to suppress ventricular arrhythmias and the safety of LX2020 in patients with ACM and a mutation in the PKP2 gene." (PMID 39684857, 2024). "The susceptibility to sustained ventricular arrhythmias mildly increased due to TAC surgery, with only slightly higher levels in PKP2-Hz TAC than in WT TAC mice (WT TAC vs. PKP2-Hz TAC; 10% vs. 20%)." (PMID 31438494, 2019). "This needs to be confirmed by in vivo recordings of ventricular arrhythmias in PKP2-Hz mice during exercise, for example by telemetry." (PMID 31438494, 2019). "As endurance training decreases cardiac function and provokes ventricular arrhythmias, PKP2-Hz mice were subjected to one-month voluntary running on a treadmill." (PMID 31438494, 2019). "Desmosomal (PKP2, DSG2), lamin (LMNA) and truncating FLNC variants destabilize the cytoskeleton, activate inflammatory and adipogenic programmes and shorten action-potential duration, changes that favor ventricular arrhythmias long before global LV dilatation." (PMID 40742635, 2025). "It was rather surprising to observe that restoration of a single desmosome component, PKP2, led to significant survival benefits, improved cardiac function, reversed adverse RV remodeling, reduced ventricular arrhythmia frequency and severity, and prevented fibrosis." (PMID 38499690, 2024). "It is significant that restoration of a single component of the desmosome, PKP2, led to significant survival benefits of improved cardiac function, reversed adverse RV remodeling, ameliorated ventricular arrhythmia severity and frequency, and prevented fibrosis." (PMID 38499690, 2024). "We propose that cardiac AAV9:PKP2 could be a beneficial gene therapy approach to reduce ventricular arrhythmias, slow down adverse right ventricular remodeling, improve heart function, and reduce mortality in ARVC patients with PKP2 mutations." (PMID 38499690, 2024). "The p.Tyr168* variant in PKP2 is associated with ACM and presents in the family described with a phenotype that is exclusively malignant ventricular arrhythmias as the first symptom, which precedes any structural myocardial involvement in 20 years of follow-up." (PMID 35627167, 2022). "Patients are predisposed to a wide spectrum of clinical presentations, such as ventricular arrhythmia and SCD, which are associated with mutations in desmosome genes, such as plakoglobin (JUP), desmoplakin (DSP), plakophilin 2 (PKP2), desmoglein 2 (DSG2), and desmocollin 2 (DSC2)." (PMID 35433691, 2022).
Ventricular arrhythmia (continued). "It is known that PKP2 carriers are more likely develop ventricular arrhythmias, while a study of whole genome sequencing and transcriptome sequencing in heart transplanted ACM patients found that recessive variants in PKP2 may lead to early-onset advanced HF." (PMID 34682905, 2021). "In line with the literature we observed that PKP2-Hz hearts of mice exposed to one month of voluntary running displayed a higher vulnerability towards sustained ventricular arrhythmias, although lacking any signs of fibrosis." (PMID 31438494, 2019).